CD24 (CD24 molecule)
Diseases named in the same sentence as CD24 in open-access papers (continued):
Sharing a sentence is not in itself a finding about the gene and the disease.
tumor (continued). "Simeone similarly used CD24/CD44/EpCAM to identify a pancreatic CSC population that displayed the ability to form tumor cell spheres as well as enhanced tumor formation in nude mice." (PMID 22570653, 2012). "Enhanced tumorigenicity of marker expressing cells was confirmed by orthotopic implantation of CD44+CD24+ESA+ versus CD44−CD24−ESA− cells in NOD/SCID mice, with tumor forming potential being 100 fold higher in CD44+CD24+ESA+ cells." (PMID 24213498, 2012). "Lastly, the enhanced viral replication in the tumor xenograft derived from cancer stem-like ALDH1+CD44+CD24+ESA+ cell implantation led to a more efficient elimination of tumors, in comparison to ALDH1-CD44+CD24-ESA+ cell derived xenografts." (PMID 22901246, 2012). "CD24, on the other hand, is a highly glycosylated cell adhesion molecule that binds to P-selectin and is involved in tumour cell invasion and metastasis." (PMID 22333601, 2012). "Immunohistochemistry analysis for 202 cases of CRC showed that the expression of both CD24 and Lyn was positively correlated with tumor grade, stage, lymph node and distant metastasis." (PMID 22731636, 2012). "In this critical review, we assess the role of CD44 and CD24 in tumour initiation, development, and metastasis." (PMID 22693526, 2012). "Regulation of CD44 or CD24 expression in various cancers seems to be effective in controlling tumour initiation and inhibition of CSC population." (PMID 22693526, 2012). "The proportion of CD44+/CD24-/low tumor cells (P = 0.002), PR status (P = 0.004), basal-like feature (P = 0.007), and TNM stage (P = 0.029) were strongly correlated with DFS." (PMID 22762532, 2012). "Further investigation on the relationship between the CD44+CD24-/low expression of tumor cells and LN metastases is warranted." (PMID 23046710, 2012). "VACV GLV-1h68 strain shows higher replication in GI-101A derived CD44+CD24+ESA+ cells resulting in increased eradication of CD44+CD24+ESA+ cells derived tumor xenografts." (PMID 22901246, 2012). "In summary, CD44+CD24+ESA+ cells did support a more efficient virus replication and the higher virus titer caused more rapid tumor elimination in nude mice with CD44+CD24+ESA+ cells derived tumor xenografts." (PMID 22901246, 2012). "The proportions of CD44+/CD24- tumor cells in clinical specimens correlated significantly with lymph node involvement (P = 0.026) and PR expression (P = 0.038)." (PMID 22762532, 2012). "When all predictors were included in a Cox model (multivariate analysis), the presence of CD44+/CD24-/low tumor cells (hazard ratio, 2.237; P = 0.002), basal-like feature, and TNM stage retained their prognostic significance for OS." (PMID 22762532, 2012). "In some tumours, CD24 was localised predominantly along the plasma membrane, while in others, it was diffusely cytoplasmic." (PMID 23028444, 2012). "Limiting dilution transplantation experiments validate that CD24+/ALDH1+/CD44high cells have a significantly greater tumor initiating ability than CD24+/ALDH1-/CD44low cells." (PMID 22452810, 2012). "It is well noted that tumor cells with CD44+CD24-/low expression not only possess malignant behavior as other tumor cells, but also share with normal stem cells the capacity for self-renewal." (PMID 23046710, 2012). "Several ligands of CD24, including P-selectin and Siglec-10, have been identified and are found to be crucial for tumor development." (PMID 22731636, 2012). "Higher proportions of CD44+/CD24- tumor cells were observed in specimens from patients with (19.20%) than without (8.66%) lymph node involvement and with (21.06%) than without (13.09%) PR expression." (PMID 22762532, 2012). "While there appears to be significant overlap between CD133 positive and CD44+/CD24+ cells, this overlap appears to vary between different tumor samples with only 10 to 40% of the CD44+/CD24+ cells expressing CD133." (PMID 22570653, 2012).
tumor (continued). "In the present study, the Cox multivariate analysis showed that CD24, tumor distant metastasis and tumor stage were independent prognostic factors of CRC patients." (PMID 22731636, 2012). "We found that a significantly higher proportion of secondary than primary lesions were positive for CD44+/CD24-/low tumor cells (26.9% versus 7.0%, P < 0.05)." (PMID 22762532, 2012). "When all predictors were included in a Cox model (multivariate analysis), the presence of CD44+/CD24-/low tumor cells (hazard ratio, 1.931; P = 0.011), PR status, basal-like feature, and TNM stage retained their prognostic significance for DFS." (PMID 22762532, 2012). "By 22 weeks after implantation, the tumor size had reached 700 mm3 in volume in contrast to 200 mm3 of tumors derived from CD44+CD24-ESA+ cells." (PMID 22901246, 2012). "Mice carrying cancer stem-like cell tumor xenografts were efficiently colonized and their tumors were more rapidly eradicated than tumors grown from ALDEFLUOR-negative and CD24- tumor cell population." (PMID 22901246, 2012). "To determine the proportion of tumorigenic CD44+/CD24- cells within each tumor, we scanned for the presence of permanent red staining without any diaminobenzidine interference." (PMID 22762532, 2012). "We isolated tumor-initiating cells (TICs) by sorting for CD24+/CD44high/ALDH1+ cells from TNBC (TNBC-TICs) and TPBC (TPBC-TICs) stable cell lines." (PMID 22452810, 2012). "Limiting dilution transplantation experiments were then performed to validate that the CD24+/ALDH1+/CD44high cells do in fact have greater tumor initiating ability than CD24+/ALDH1-/CD44low cells." (PMID 22452810, 2012). "During metastasis, tumor cells pass through the blood stream by binding to platelets or to endothelial cells via the interaction between CD24 and P-selectin." (PMID 21676268, 2011). "Using this strategy, high activity of the intracellular enzyme, aldehyde dehydrogenase (ALDH), and the cell surface markers CD133 and co-expressed CD44/CD24 have been shown individually shown to possess tumor-initiating properties in different studies." (PMID 21695188, 2011). "A higher proportion of CD44+/CD24− tumour cells and ALDH1 positivity was associated with higher histologic grade (P=0.002 and P=0.007, respectively) and ER negativity of tumour (P<0.001 and P<0.001, respectively)." (PMID 21559013, 2011). "Tumours with a CD44+/CD24- phenotype are highly invasive with targeted reduction of CD44 markedly reducing malignant characteristics of tumours in vivo." (PMID 21713035, 2011). "CD24 has been repeatedly detected in gene expression profiling to identify genes which expression correlates with tumorigenesis and tumor progression." (PMID 21359202, 2011). "CD44+/CD24- is considered a cancer stem cell or tumor initiating cell signature, and high CD44/CD24 ratios are characteristic of aggressive Claudin-low tumors and cell lines." (PMID 21931769, 2011). "CD24 increases tumor cell proliferation and adhesion to fibronectin, collagen I, IV and laminin through the activation of alpha3beta1 and alpha4beta1 integrin activity." (PMID 21676268, 2011). "H&E staining of CD44+CD24+ESA+ CSC tumors formed in nude mice revealed similar tumor phenotype with that of primary human tumors." (PMID 21304978, 2011). "NDRG2 exerted anti-tumor activity by regulating CD24, a molecule that mediates cell-cell interaction, tumor proliferation and adhesion." (PMID 21676268, 2011). "The CD44+CD24-/low cells were able to form tumours in NOD/SCID mice from fewer cells than the mixed population with 10- to 50-fold enrichment for this ability." (PMID 22112299, 2011). "All examined xenograft tumors revealed very small overlap between CD44+/CD24+ and ALDHhigh or ALDHlow cell populations, representing 0.015% and 0.11% respectively, of all viable, human tumor cells." (PMID 21695188, 2011).
tumor (continued). "CD24 is able to promote tumor cell proliferation and alter the adhesive properties of tumor cells to P-selectin, fibronectin, collagens type I and IV, and laminin." (PMID 21359202, 2011). "Higher scores of cytoplasmic CD24 were observed in tumor tissues compared to normal adjacent tissues." (PMID 21676268, 2011). "Data showed that NDRG2 expression was decreased in tumor tissues compared to normal adjacent tissues; however, CD24 was enhanced in tumor tissues." (PMID 21676268, 2011). "There were more tumours with a maximum Allred score of 8 for the CD44+CD24-/low phenotype than the other CSC markers (4% for CD44+CD24-/low and ≤1% for the other CSC markers)." (PMID 22112299, 2011). "These CD44+/CD24+/EpCAM+ cells presented self renewal capacity, tumor initiation and up-regulated of the Hedgehog signaling pathway." (PMID 24281178, 2010). "It is currently accepted that absence of CD24 on the tumor cell surface inhibits proliferative response and induces apoptosis in tumor cells, while up-regulation of CD24 promotes cell proliferation to increase tumor growth and metastasis." (PMID 20950440, 2010). "The loss of ERα expression in SP cells or in small transplanted tumours is consistent with this report by Polyak and co-workers who found ERα downregulated in CD44+ compared with CD24+ cells." (PMID 20145614, 2010). "CXCR4 and SDF-1 are candidate factors that involved in the cross-talk of the tumor-niche interaction of CD44+CD24- cells." (PMID 20569497, 2010). "Either way, this is the first report on the embryonic antigen GDF3 which is an inducer of CD24 and joins tumor cell proliferation." (PMID 20950440, 2010). "Seven days after injection, the tumor was excised, and the tumor cells were stained with anti-CD24 and -CD44 antibodies." (PMID 20950440, 2010). "MCF-7 CD24-/low/CD44+ tumor-initiating cells, grown as mammospheres, have previously been shown to be more resistant to ionizing radiation than the general population of MCF-7 adherent cells." (PMID 20525204, 2010). "An association between CD44+/CD24- frequency and a basal tumor phenotype has already been reported and interestingly we observed an increased frequency of CD44+/CD24- cells in the brain metastases compared to their matched primaries." (PMID 20604919, 2010). "We showed that cells derived from CD24−/low/CD44+ populations resulted in tumours larger than those of CD24+/CD44+ control populations." (PMID 19997106, 2010). "The ESA+CD44+CD24-/low cells had up to 100- to 1000-fold greater tumor-initiating capability than the MCF-7 cells." (PMID 21192833, 2010). "We monitored tumour formation by in vivo imaging and found that the luciferase activities of the tumours derived from CD24−/low/CD44+ cell populations treated with DHMEQ were significantly decreased compared with that of untreated cell-derived tumours." (PMID 19997106, 2010). "FACS analysis showed that tumor cells with GDF3-expressing vector contained more CD24 and CD44 double-positive cells than those transfected with the empty vector." (PMID 20950440, 2010). "CD44+/CD24- cells comprised an average of 0.25% (N = 2) from primary tumors and 16.4% (N = 4) from tumor derived sphere culture, a 65-fold increase." (PMID 20615238, 2010). "Since CD24 is a pattern-recognition receptor to participate in poor prognosis in cancer patients, we discussed the possible role of the GDF3-CD24 pathway in tumor progression." (PMID 20950440, 2010). "HE staining revealed that tumours derived from CD24−/low/CD44+ and unsorted cells showed a similar histology, namely, exclusively invasive patterns with a variety of morphologies and the stromal component." (PMID 19997106, 2010). "a group of genes identified as being differentially expressed in a population of tumor initiating cells (CD44+CD24-) as compared to normal breast epithelium." (PMID 19327144, 2009).
tumor (continued). "Analysis of surface markers during long term tumor culture of primary HBCEC (more than 476d) demonstrated a prominent expression of CD24, CD44 and MUC1 (CD227)." (PMID 19751512, 2009). "While additional work is needed to elucidate the biological significance of these proteins, CD24 and CD74 expressed only in small proportion of cells indicating tumor heterogeneity and subtypes of tumor initiating cells (CD24+/CD44+) present in HNSCC." (PMID 19602232, 2009). "Examples are 'PI3K/AKT', 'KRAS', 'PTEN', 'WNT-beta catenin' and 'MAPK signaling' pathways, as well as a group of genes specific of human tumor initiating cells (CD44+CD24-)." (PMID 19327144, 2009). "The CD44+CD24-/low cells represent a small subclass within the tumor but are considered to be the actual tumorigenic cells whereas the rest, called nontumorigenic, have little or no such ability." (PMID 19664271, 2009). "These previously reported differences in expression of CD24 in different tumor types and in normal mouse mammary epithelium support our search for the role of CD24- cells in combination with a more established marker, CD44, in BRCA1-deficient tumors." (PMID 18241344, 2008). "To determine the proportion of putative tumorigenic CD44+/CD24- cells within each tumor, we scanned for the presence of Permanent Red staining without any DAB interference." (PMID 18559090, 2008). "Remarkably, the A1.1 cell line which is derived from 0_A1 tumor showed up to 2.6% CD44+/CD24-/low cells." (PMID 18394172, 2008). "CD44+/CD24- tumor cells were detected in 31% (75/240) of the tumors, with the proportion of this phenotype ranging from only a few cells to almost all tumor cells." (PMID 18559090, 2008). "CD44+CD24− cells form colonies in soft agar and form tumours in NOD/SCID mice when as few as 100 cells are injected." (PMID 18268494, 2008). "Our results further indicate that CD24 is involved in migration in MCF-7 cells, and imply that tumor progression can be inhibited by CD24 cross-linking." (PMID 18433506, 2008). "CD24 is an adhesion molecule and during tumor progression, adhesion to the extracellular matrix (ECM) is the initial step for invasion and metastasis." (PMID 18433506, 2008). "We also determined the proportion of CD44-/CD24+ and double-positive (CD44+/CD24+) cells in each tumor." (PMID 18559090, 2008). "In contrast to our findings, Schabath and colleagues showed that MDA-MB-231 cells (used as a control in this study) transfected to express CD24 had reduced migration and tumor growth in NOD/SCID mice." (PMID 18433506, 2008). "Tumour formation with DU145 showed an increase in the ability of CD44+CD24− cells to form tumours (5/5) in comparison with CD44+CD24+ cells (3/5)." (PMID 18268494, 2008). "CD44+/CD24- cells were detected in 31% of the tumors, ranging in proportion from only a few to close to 100% of tumor cells." (PMID 18559090, 2008). "To study this relation in more depth, we used five protein markers available for 232 out of the 240 cases with CD44/CD24 data to define five tumor subgroups." (PMID 18559090, 2008). "Immunocytochemically, the tumour cells resemble activated germinal centre B cells and express IgM, pan B cell markers like CD 19, CD 20, CD24, 1a, as well as CD10." (PMID 17615068, 2007). "Presence of CD24 in cytoplasm of tumour cells has been explained by stimulated synthesis of the protein." (PMID 16892043, 2006). "Immunohistochemical analysis also demonstrated increased expression of CD24 antigen in malignant versus benign tumour tissue." (PMID 16969345, 2006). "Other study groups found the following results for other tumor entities: Fogel shows that CD24 was expressed in four of six breast cell lines (66.7% sensitivity)." (PMID 16539730, 2006). "In a complementary study, Abraham and coworkers reported that the prevalence of CD44+/CD24- cells (tumors with >10% of CD44+/CD24- cancer cells) in 22% of tumor samples." (PMID 17062128, 2006).
tumor (continued). "Taking groups three and four together, 45% of tumours showed a high level of expression of CD24 in this study." (PMID 12610508, 2003). "CD24 has been identified as a ligand to P-selectin, and it is conceivable that this function contributes to a more aggressive metastatic behaviour of CD24-positive tumour cells, as in vitro evidence suggests." (PMID 12610508, 2003). "For CD24 expression, we found a statistically significant difference of median survival time for tumours with low levels (0, 1+) compared to tumours with high levels (2+, 3+) of CD24 expression with 23 months vs 38 months (P=0.033)." (PMID 12610508, 2003). "All three parameters, tumour grading (P=0.011), disease stage (P=0.006) and CD24 expression (P=0.024) proved to be independent prognostic factors for shortened overall survival in NSCLC." (PMID 12610508, 2003). "Patients whose tumours had a high CD24 expression showed a significantly shorter median survival time of 23 months vs 38 months (P=0.033, log-rank test)." (PMID 12610508, 2003). "Additionally, by binding to Siglec-10 on macrophages, CD24 on the surface of TC cells would aid tumor cells in escaping immune surveillance." (PMID 41584035, 2026). "Genetic and pharmacologic perturbations revealed that microglial phenotypes could be shifted by inhibiting TGFβ signaling or by deleting the tumor cell surface antigens CD24 and CD47." (PMID 41369553, 2026). "CD24 plays pluripotent roles in tumorigenesis, stemness, and tumor immune escape." (PMID 41585138, 2026). "However, in tumor cells, CD24 can be detected on the cell membrane, cytoplasm, and even the nucleus." (PMID 40486886, 2025). "Thus, artificial suppression of SOX9 in PANC-1 cells decreased the number of cells carrying CD44 and CD24 markers, as well as decreased the ability of the cells to form spheres (sphere formation rate) and to initiate tumor in nude mice." (PMID 40141294, 2025). "Further, CD24 can regulate the malignant behavior of tumor cells, including migration and invasion." (PMID 40486886, 2025). "Similarly, the patients with a low CD3+ TIL density and a high CD24/CD44 coexpression in tumor cells had the worst DFS, MFS, and OS, with a median of 3.9 years for both DFS and MFS." (PMID 40647395, 2025). "In a preclinical model of CD24+ solid tumors, blocking the CD24-Siglec-10 interaction with an anti-CD24 monoclonal antibody (mAb) led to increased TAM-associated phagocytosis in vitro, as well as TAM-dependent tumor growth reduction and enhanced survival in vivo." (PMID 40770672, 2025). "In 38% of the cases, the tumor cells coexpressed CD24 and CD44." (PMID 40647395, 2025). "Additionally, the elevated CD24 expression was significantly associated with EMT by facilitating cellular plasticity and thus enhancing tumor invasiveness and metastasis." (PMID 40821783, 2025). "Moreover, the CD24/Siglec-10 axis enhances the tumor’s resistance to chemotherapy, particularly cisplatin, by reducing apoptosis in cancer cells." (PMID 40330466, 2025). "CD24, highly expressed on various tumor cells, binds to Siglec-10 on macrophages, transmitting a “don't eat me” signal that inhibits phagocytosis and facilitates tumor immune escape." (PMID 41209563, 2025). "Overall, while STAT3 inhibition did not significantly impact cell viability, proliferation, or CD44 induction after HER2 inhibition, JAK1 inhibition appeared to sensitize cells to HER2 inhibition and impair proliferation during the recovery phase in CD24+/CD44+ tumor cells." (PMID 40430044, 2025). "Our findings support the notion that targeting CD24 could be a promising strategy for enhancing anti-tumor activity, particularly in immune “cold” TNBC tumors." (PMID 40783744, 2025). "CD24 can alter cancer development by modulating the inner activity of tumor cells." (PMID 40486886, 2025). "These vesicles display surface anti-CD24 nanobodies, enabling tumor-specific targeting." (PMID 41281650, 2025).